UBE2T (ubiquitin conjugating enzyme E2 T)
Diseases named in the same sentence as UBE2T in open-access papers (continued):
Sharing a sentence is not in itself a finding about the gene and the disease.
gastric cancer (continued). "For instance, 14, 15, and 16 inhibit the UBE2T/FANCL-mediated ubiquitination of FANCD2 in the FA pathway, while 17 targets gastric cancer and 18 targets pancreatic cancer." (PMID 39791716, 2024). "M435-1279, a novel UBE2T inhibitor that inhibits the over-excitation of the Wnt/β-catenin signaling pathway by blocking the UBE2T-mediated degradation of RACK1, has been shown to play a role in gastric cancer and provides insights for the treatment of CC." (PMID 38521878, 2024). "This possibility is partly supported by a recent study, which found that in gastric cancer cells, RACK1 is a short-lived protein that can be ubiquitinated and degraded by the ubiquitin-conjugating enzyme UBE2T." (PMID 37848434, 2023). "A recent study revealed that UBE2T facilitated ubiquitin-dependent degradation of RACK1, a key scaffold protein stabilizing the β-catenin destruction complex in gastric cancer, leading to accumulation of β-Catenin and activation of the Wnt/pathway." (PMID 36357897, 2022). "We therefore examined the effects of UBE2T on the invasive and metastatic abilities of AGS and SGC-7901 gastric cancer cells." (PMID 28427240, 2017). "UBE2T mRNA expression, which was measured in SGC-7901, MKN-45, MGC80-3, and BGC823 gastric cancer cells using real-time PCR, was high in all of the gastric cancer cells and positively correlated with measures of malignancy." (PMID 28427240, 2017). "UBE2T expression was highest in MKN-45 gastric carcinoma cells isolated from poorly-differentiated adenocarcinoma, while MGC80-3 gastric carcinoma cells had the lowest expression." (PMID 28427240, 2017). "Additionally, UBE2T promotes β-catenin nuclear translocation through the ubiquitin-mediated degradation of RACK1, facilitating gastric cancer progression." (PMID 39791716, 2024). "Decreased CDH1 expression is positively correlated with gastric cancer progression; the decreased CDH1 (E-Cadherin) expression observed here might partially explain the ability of UBE2T knockdown to attenuate gastric tumor formation and growth." (PMID 28427240, 2017). "Next, we examined whether siRNA-mediated suppression of UBE2T expression in SGC-7901 and BGC-823 cells inhibited gastric cancer progression." (PMID 28427240, 2017). "Among 29 gastric carcinoma tissues, UBE2T gene expression was increased in 23, and unchanged in 6, tumor samples compared to para-carcinoma tissue; no tumor samples exhibited UBE2T down-regulation." (PMID 28427240, 2017). "Furthermore, UBE2T-mediated degradation impacts other signaling proteins essential for cell cycle progression and epithelial–mesenchymal transition (EMT), further enhancing the invasiveness of gastric cancer." (PMID 39791716, 2024). "However, no systemic studies of UBE2T in gastric cancer that include in vitro and in vivo models along with clinical samples have yet been conducted." (PMID 28427240, 2017). "Another group demonstrated that an ubiquitin-conjugating enzyme Ube2T directly interacts with RACK1 and induces RACK1 ubiquitination and degradation independent of the E3 ligase in gastric cancer cells." (PMID 35265209, 2022).
lung adenocarcinoma (17 papers, 2017 to 2026). A carcinoma that arises from the lung and is characterized by the presence of malignant glandular epithelial cells. "In silico analyses from TCGA cohorts have revealed a positive correlation between phosphorylated ERK and UBE2T transcript levels in colorectal cancer and lung adenocarcinoma." (PMID 41486508, 2026). "NEDD4L inhibited lung adenocarcinoma cell progression in vitro and in vivo via inducing the ubiquitination‐mediated Ubiquitin‐conjugating enzyme E2T (UBE2T) degradation, which repressed PI3K‐Akt signalling." (PMID 38526036, 2024). "Further, high expression levels of UBE2T, TK1, and KPNA2 were associated with poor survival rates of patients with lung adenocarcinoma in TCGA data." (PMID 35884546, 2022). "For Instance, the E2 enzyme UBE2T inhibited CD8+ T-cell infiltration and expression of immune-promoting factors (IFN-γ, TNF-α and IL-2) in lung adenocarcinoma by activating the glycolytic pathway upon binding to FOXA1." (PMID 40183093, 2025). "NEDD4L is a new E3 ligase of UBE2T that inhibits PI3K-AKT signal transduction by inducing ubiquitination-mediated UBE2T degradation, which could inhibit the progress of lung adenocarcinoma cells." (PMID 37795365, 2023). "A number of studies have indicated that Ubiquitin-conjugating enzyme E2T (UBE2T), as an oncogene, promotes progression and metastasis of lung cancer, including lung adenocarcinoma (LUAD), but it is completely unknown whether and how UBE2T is ubiquitylated and degraded, and by which E3 ligase." (PMID 34838005, 2021).
prostate carcinoma (16 papers, 2015 to 2026). A carcinoma that arises from epithelial cells of the prostate gland. "Survival association with UBE2T was also demonstrated in breast, osteosarcoma, nasopharyngeal carcinoma, prostate cancer, and esophageal cancer." (PMID 36357897, 2022). "Moreover, higher level of UBE2T expression is associated with poorer prognosis of prostate cancer patients." (PMID 26308072, 2015). "In summary, this study reveals the molecular mechanism by which AKR1C3 is involved in metabolic reprogramming to promote radioresistance in prostate cancer through PKM2/UBE2T." (PMID 41912503, 2026). "The oncogenic effect of UBE2T also was reported in osteosarcoma, nasopharyngeal carcinoma, prostate cancer, and esophageal cancer." (PMID 36357897, 2022). "It was shown that ubiquitin conjugating enzyme E2T (UBE2T) exhibits oncogenic properties while genetic ablation of Ube2o (ubiquitin conjugating enzyme E2O) impairs progression of prostate cancer." (PMID 33572160, 2021). "In prostate cancer, UBE2T mediated the proliferation and epithelial-mesenchymal transition (EMT) of prostate cancer cells by regulating vimentin." (PMID 34257599, 2021). "Prostate cancer tissue array analysis confirmed upregulation of UBE2T in prostate cancer, especially these with distant metastasis." (PMID 26308072, 2015). "Increased expression of ubiquitin-conjugating enzyme E2T (UBE2T) is reported in human prostate cancer." (PMID 26308072, 2015). "Ectopic expression of UBE2T significantly promotes prostate cancer cell proliferation, motility and invasion, while UBE2T depletion by shRNA significantly inhibits these abilities of prostate cancer cells." (PMID 26308072, 2015). "The putative role of UBE2T as an oncogene in cancer development was supported by the observations that aberrant expression of UBE2T in bladder, lung and prostate cancers." (PMID 26308072, 2015). "Taken all together, we concluded that UBE2T promote the proliferation of prostate cancer cells in vivo and in vitro." (PMID 26265437, 2015). "Collectively, we identify critical roles of UBE2T in prostate cancer development and progression." (PMID 26308072, 2015). "However, whether UBE2T plays any functional role in prostate cancer development remains unknown." (PMID 26308072, 2015). "Furthermore, the expression of UBE2T (FANCT), which is needed for the ubiquitination of FANCI and which we have also shown to be upregulated in prostate cancer cells resistant to the anti-androgen therapy drug enzalutamide, was significantly reduced." (PMID 38023254, 2023). "Moreover, similar studies of prostate cancer showed that increased UBE2T expression promoted proliferation and was sufficient to induce EMT of prostate cancer cells, as well as enhanced tumour growth in prostate cancer xenograft mouse models and prostate cancer metastasis." (PMID 27729585, 2016).
lung carcinoma (14 papers, 2017 to 2024). "UBE2T is significantly associated with poor prognosis in lung carcinoma." (PMID 34461934, 2021). "For instance, our group demonstrated that UBE2T stimulated autophagy in lung cancer cells in a preceding study." (PMID 36621836, 2023). "The results were similar to the previous study that UBE2T was over-expressed in lung cancer, which was confirmed by western blotting, qRT-PCR, and immunohistochemistry." (PMID 35543375, 2022). "Spheroids composed of 344SQ murine lung cancer cells with either control or Ube2t-, Tk1-, Cxcl12-, and Kpna2-knockdown CAFs were seeded into collagen gel, and spheroid invasion was then monitored for 2 days." (PMID 35884546, 2022). "In this study, we first examined the expression levels of UBE2T in eight lung cancer cell lines and a normal human lung epithelial cell line." (PMID 34461934, 2021). "In this study, we found that UBE2T was upregulated in most tested lung cancer cell lines when compared with control cells." (PMID 34461934, 2021). "UBE2T was highly expressed in lung cancer, and its protein expression was negatively correlated with the survival of lung cancer patients." (PMID 34838005, 2021). "We found that UBE2T stimulated proliferation and autophagy, and silencing this gene abolished autophagy in lung cancer cells." (PMID 34461934, 2021). "A number of previous literatures have documented that UBE2T is highly expressed in lung cancer, which is diverse in molecular mechanism and has a carcinogenic effect in function, and is a prognostic risk factor for considerable types of malignant tumors such as lung cancer." (PMID 39553728, 2024). "Therefore, we developed and validated a multiple gene signature by considering UBE2T and its relevance in autophagy in lung cancer." (PMID 34461934, 2021). "Lentiviral vectors were used to mediate UBE2T depletion or overexpress UBE2T in lung cancer cells." (PMID 34461934, 2021). "This study aims to explore the function and clinical relevance of UBE2T in lung cancer." (PMID 34461934, 2021). "Previous studies have demonstrated that UBE2T is overexpressed in lung cancer." (PMID 34461934, 2021). "Moreover, UBE2T was shown to display radio-sensitization effect on osteosarcoma and lung cancer cells." (PMID 33087136, 2020). "In addition to its role in Fanconi anemia, UBE2T is increasingly recognized as a critical factor during carcinogenesis in human nasopharyngeal, prostate, breast, and lung cancer." (PMID 28427240, 2017). "In accordance with other reports, UBE2T has been connected to EMT in several types of cancers, such as glioblastoma, gastric, and lung cancer." (PMID 34614271, 2022). "UBE2T has been correlated with EMT induction in many types of cancer such as glioblastoma, gastric, and lung cancer." (PMID 34614271, 2022). "Although most studies have reported that UBE2T and NEDD4L are involved in the growth regulation of lung cancer cells, their cross-role in the synergistic regulation of cancer cell growth has never been reported before." (PMID 34838005, 2021). "To explore the downstream signaling pathway of UBE2T, we performed GSEA on lung cancer cell lines downloaded from the CCLE database." (PMID 34461934, 2021). "UBE2T may have previously been shown to promote both autophagy and proliferation, which raises the possibility that by inhibiting this gene, lung cancer cells may not go through autophagy." (PMID 36245987, 2022).
liver cancer (10 papers, 2018 to 2025). An epithelial or non-epithelial malignant neoplasm that arises from the liver. "UBE2T is found to potentiate liver cancer stem cells’ functions through direct regulation of Mule-mediated β-catenin degradation." (PMID 33934686, 2021). "Moreover, the association between high expression of UBE2T or simultaneously high expression of UBE2T and SENP1 with lower survival rate was showed by TCGA database and KM plotter liver cancer dataset." (PMID 31969492, 2020).
glioblastoma (8 papers, 2020 to 2026). The most malignant astrocytic tumor (WHO grade IV). "In glioblastoma, elevated FA pathway activity, particularly through UBE2T‐dependent regulation, has been associated with enhanced repair capacity and reduced responsiveness to DNA‐damaging therapies, positioning this pathway as a potential target to overcome chemoresistance." (PMID 41486508, 2026). "High UBE2T expression has been correlated with poor survival and temozolomide resistance in glioblastoma, while MAPK/ERK hyperactivation promotes replication stress tolerance and radioresistance." (PMID 41486508, 2026). "UBE2T is an oncogene overexpressed in various cancers, including Ewing’s sarcoma (ES), pancreatic cancer (PC), glioblastoma (GBM), head and neck squamous cell carcinoma (HNSC), and colorectal cancer (CRC)." (PMID 39791716, 2024).
osteosarcoma (8 papers, 2020 to 2024). A usually aggressive malignant bone-forming mesenchymal neoplasm, predominantly affecting adolescents and young adults. "In Osteosarcoma and renal cell carcinoma, UBE2T overexpression increased the capacity of proliferation via PI3K/AKT pathway, and was associated with aggressiveness, metastasis and poor prognosis." (PMID 34838005, 2021). "UBE2T downregulation has been shown to enhance the radiosensitivity of osteosarcoma in vitro and in vivo." (PMID 34830778, 2021). "One study found that UBE2T is also aberrantly overexpressed in osteosarcoma tissues and cell lines." (PMID 39062505, 2024). "In addition, some studies have shown a downregulation of UBE2T in renal cell carcinoma and osteosarcoma cells." (PMID 36088429, 2022). "Molecules such as UBE2T, E3 ubiquitin ligase adaptor SPOP, USP9X, USP22, and BAP1 are involved in regulating the proliferation, migration, and invasion of osteosarcoma cells through modulation of the PI3K/Akt signaling pathway." (PMID 39062505, 2024). "For instance, UBE2T stimulated the proliferation and invasion of cancer cells through the PI3K/AKT pathway in osteosarcoma cells." (PMID 34257599, 2021). "UBE2T promotes the proliferation, migration, and invasion of osteosarcoma cells through positive regulation of the PI3K/Akt signaling pathway, suggesting that UBE2T may serve as an important target in osteosarcoma therapy." (PMID 39062505, 2024).
bladder cancer (7 papers, 2020 to 2025). "High expression of UBE2T in bladder cancer is associated with enhanced proliferation and colony formation ability of bladder cancer cells when UBE2T is depleted." (PMID 39367897, 2025). "UBE2T is highly expressed in bladder cancer, and its deletion significantly inhibits the proliferation and colony-forming ability of bladder cancer cells." (PMID 36088429, 2022). "Study has shown that UBE2T was upregulated in bladder cancer tissues and cell lines, and knockdown of UBE2T reduced the proliferation of bladder cancer cells, induced cell cycle arrest in the G2/M phase, and increased the apoptosis." (PMID 34703898, 2021). "Reversely, the depletion of UBE2T in bladder cancer suppressed tumor growth and concomitantly induced cell cycle arrest and apoptosis." (PMID 34257599, 2021). "Gong and colleagues observed that the knockdown of UBE2T inhibited the proliferation of bladder cancer cells and led to cell cycle arrest and apoptosis." (PMID 34257599, 2021). "UBE2T is over-expressed in bladder cancers, and UBE2T depletion significantly suppresses the proliferation and colony formation of bladder cancer cells." (PMID 32491994, 2020). "UBE2T knockout can significantly inhibit the proliferation and colony formation of bladder cancer cells, induce cell cycle arrest, and increase the rate of apoptosis, which might be related to the fact that UBE2T is the target gene promoted by the E2F transcription factor." (PMID 33810518, 2021).
non-small cell lung carcinoma (7 papers, 2021 to 2024). A group of at least three distinct histological types of lung cancer, including non-small cell squamous cell carcinoma, adenocarcinoma, and large cell carcinoma. "In non-small cell lung cancer, UBE2T indirectly activates this pathway by ubiquitinating FOXO1, aiding tumor cell survival and contributing to resistance against radiotherapy." (PMID 39791716, 2024). "More importantly, increasing evidence has shown that UBE2T is closely related to non-small cell lung cancer progression." (PMID 35543375, 2022). "Less explored so far, our group recently reported first evidence that UBE2T is amplified in BC and non-small cell lung carcinomas, in which it was related to a detrimental outcome." (PMID 33671201, 2021). "UBE2T silencing inhibited non-small cell lung cancer cell proliferation and invasion by suppressing the Wnt/β-catenin signaling pathway." (PMID 33937050, 2021). "Cervical cancer cells gain the mesenchymal phenotype and lose the epithelial characteristic features during tumor progression, and UBE2T promoted the ubiquitination-mediated FOXO1 degradation to facilitate the epithelial-mesenchymal transition of non-small cell lung cancer." (PMID 34703898, 2021). "Although a previous study has shown that UBE2T was elevated markedly in non-small cell lung cancer tissues and ranked first according to the hazard ratio in the survival analysis, the functional role and molecular mechanism of UBE2T in LUAD proliferation and metastasis remain unknown." (PMID 35543375, 2022).
pancreatic cancer (7 papers, 2022 to 2026). "For example, in pancreatic cancer cells with KRAS G12D mutations, the activity of the axis up-regulates ubiquitin-conjugating enzyme UBE2T and modulates the pentose phosphate pathway, which is important for the carbon metabolism of cancer cells." (PMID 40699853, 2025). "1,2,3,4,6-O-Pentagalloylglucose 18 is a naturally occurring galloyl-β-d-glucose compound that has emerged as a promising inhibitor of UBE2T, particularly in the context of pancreatic cancer treatment." (PMID 39791716, 2024). "UBE2T has been recently identified as an oncogenic protein that is highly expressed in pancreatic cancer tissues and cell lines, and overexpression of UBE2T significantly promotes pancreatic cancer cell proliferation, migration, and invasion." (PMID 35272681, 2022).
renal cell carcinoma (7 papers, 2021 to 2024). "For example, UBE2T was shown to upregulate EMT in renal cell carcinoma and NSCLC cancer." (PMID 36357897, 2022). "UBE2T promoted the proliferation of renal cell carcinoma cells by regulating P13K/AKT signaling, suggesting that it might be a novel target for the treatment of patients with renal cell carcinoma." (PMID 33810518, 2021).